ILF2 (interleukin enhancer binding factor 2)
Diseases named in the same sentence as ILF2 in open-access papers (continued):
Sharing a sentence is not in itself a finding about the gene and the disease.
metastatic melanoma (1 paper, 2021). A melanoma that has spread from its primary site to another anatomic site. "Enhanced ILF2 mRNA expression in metastatic melanoma patients is significantly associated with a poor prognosis." (PMID 34709752, 2021). "Enhanced ILF2 mRNA expression was associated with poor outcomes in metastatic melanoma patients." (PMID 34709752, 2021). "Consistently, ILF2 knockdown significantly increased the number of nuclei observed per cell in metastatic melanoma cell lines (p < .01)." (PMID 34709752, 2021). "U2AF2 knockdown blocked the enhanced cell proliferation (p < .0001) and colony formation (p < .0001) induced by ILF2‐OV in metastatic melanoma." (PMID 34709752, 2021). "The overexpression of ILF2 (ILF2‐OV) promotes proliferation in metastatic melanoma cells, whereas ILF2 knockdown decreases proliferation by blocking the cell cycle." (PMID 34709752, 2021). "Fifty‐five per cent of the metastatic melanoma tumours showed increased copy number of the ILF2 gene." (PMID 34709752, 2021). "Moreover, ILF2 depletion promotes cell cycle arrest in the G1 phase and enhances apoptosis in metastatic melanoma cells." (PMID 34709752, 2021). "We then assessed the CNV data from the TCGA SKCM database to determine whether genomic amplifications may be responsible for promoting ILF2 upregulation in metastatic melanoma." (PMID 34709752, 2021). "The upregulated ATM activation observed in ILF2‐OV cells could explain the ILF2‐induced effects on proliferation, resistance to DNA‐damage agents, and high efficiency of HR in metastatic melanoma cells." (PMID 34709752, 2021). "Moreover, RAD50 knockdown blocked the enhanced cell proliferation induced by ILF2‐OV in metastatic melanoma." (PMID 34709752, 2021). "Moreover, high mRNA levels of ILF2 and U2AF2 were associated with poor outcomes in metastatic melanoma patients." (PMID 34709752, 2021). "Paradoxically, metastatic melanoma cells with ILF2‐OV were more sensitive to ATM inhibitors." (PMID 34709752, 2021). "Therefore, we hypothesised that ILF2 overexpression may promote enhanced DDR in metastatic melanoma." (PMID 34709752, 2021). "In summary, ILF2 forms a complex with U2AF2 to promote cell proliferation and colony formation in metastatic melanoma." (PMID 34709752, 2021). "Our results demonstrated the regulatory role of ILF2 controlling the expression of RAD50 and ATM pathway activation, which consequently enhanced the efficiency of DDR by activating HR in metastatic melanoma cells." (PMID 34709752, 2021). "Consistently, we observed that both ILF2 and U2AF2 proteins showed nuclear localisation in metastatic melanoma cell lines." (PMID 34709752, 2021). "ILF2 mRNA average levels were significantly increased in stage III (1.64 fold‐change) and stage IV (1.87 fold‐change) metastatic melanoma compared to primary tumour tissues." (PMID 34709752, 2021). "Higher ILF2/U2AF2 expression and a consequently significantly higher expression of RAD50 were observed in metastatic melanoma tissues compared to primary tissues." (PMID 34709752, 2021). "Our results show that ILF2 and U2AF2 may have implications in RAD50 and ATM mRNA processing in metastatic melanoma." (PMID 34709752, 2021). "In conclusion, RAD50 plays a significant role as a downstream effector of ILF2, and it may have implications in controlling DDR in metastatic melanoma cells." (PMID 34709752, 2021).
metastatic tumour (1 paper, 2024). "We found that ILF2 was most highly expressed in metastatic tumour cells (MTCs), except for renal cell carcinoma (RCC)." (PMID 38943472, 2024).
Premature ovarian insufficiency (1 paper, 2021). Amenorrhea due to loss of ovarian function before the age of 40. "The down-regulated lncRNA HCP5 in the human premature ovarian insufficiency (POI) model can partially cause dysfunction of granulosa cells due to impaired DNA damage repair mediated by Y-box binding protein 1 and ILF2." (PMID 34944367, 2021).
prostate adenocarcinoma (1 paper, 2023). "In human prostate adenocarcinoma, NUSAP1 and ILF2 mRNA expression levels are positively correlated, elevated, and associated with poor clinical outcomes." (PMID 37047232, 2023).
prostate carcinoma (1 paper, 2023). A carcinoma that arises from epithelial cells of the prostate gland. "Analysis of NUSAP1, ILF2, and DHX9 in the TCGA dataset parallels our findings, substantiating the important role of the NUSAP1 and ILF2 interaction in prostate cancer aggressiveness." (PMID 37047232, 2023). "To determine whether NUSAP1, ILF2, DHX9, and HNRPC are associated with R-loops in prostate cancer cells, we performed immunoprecipitation using the S9.6 antibody in LNCaP cells." (PMID 37047232, 2023). "To confirm the interaction of NUSAP1 and ILF2, DHX9, and HNRPC, we transiently transfected LNCaP and DU145 prostate cancer cell lines with empty vector or Flag-NUSAP1." (PMID 37047232, 2023). "Therefore, human localized prostate cancer samples show co-expression of NUSAP1 with its binding partners, ILF2 and DHX9." (PMID 37047232, 2023).
rhabdomyosarcoma (1 paper, 2019). A rare aggressive malignant mesenchymal neoplasm arising from skeletal muscle. "Cellular studies indicate that EV71 infection represses ILF2 mRNA expression and protein production in human leukemic monocytes (THP-1) -differentiated macrophages and human rhabdomyosarcoma (RD) cells." (PMID 31878072, 2019).
scleroderma (1 paper, 2018). Scleroderma is a rare autoimmune connective tissue disorder characterized by abnormal hardening of the skin and, sometimes, other organs. "To assess the presence of ILF2 and ILF3 autoantibodies in human disease, we screened human sera from patients with SLE, Sjögren’s syndrome or systemic sclerosis (scleroderma)." (PMID 29556082, 2018).
scrub typhus (1 paper, 2021). Scrub typhus is a rare dust mite-borne infectious disease caused by the Orientia tsutsugamushi bacterium and characterized clinically by an eruptive fever which is potentially serious. "Furthermore, the ILF2 and OAS genes were downstream of the top SNP, and the rs11184708 SNP located upstream of the PRMT6 gene, which is related to susceptibility to scrub typhus." (PMID 33807835, 2021).
Sjögren’s syndrome (1 paper, 2018). "Autoantibodies to ILF2 were detected in one Sjögren’s syndrome patient, and at a level just above cutoff in one SLE patient." (PMID 29556082, 2018). "ILF2 and ILF3 autoantibodies were also found at low frequency in human patients with SLE and Sjögren’s syndrome." (PMID 29556082, 2018).
steatosis (1 paper, 2022). Increased lipid within the cytoplasm of cells. "In contrast, overexpression of Tcea1, Rbbp4, and ILF2, respectively, could ameliorate hepatocyte steatosis." (PMID 35637971, 2022).
tumor (36 papers, 2005 to 2026). "The increased ILF2 levels were closely associated with the degree of tumor differentiation, clinical stage, and the proliferation marker MKI67." (PMID 39735599, 2024). "The overexpression of ILF2 is often associated with advanced tumor stages, poor differentiation, and increased tumor aggressiveness." (PMID 39735599, 2024). "Abnormal activation of GATAD1 and ILF2 was associated with invasive tumor characteristics." (PMID 41430036, 2025). "However, the impact of ILF2 on GC diagnosis and therapy and the association of ILF2 with GC cell growth and tumor immunity remain unclear." (PMID 38622522, 2024). "ILF2 expression is closely related to tumor cell migration and invasion, neo-angiogenesis, and patient prognosis." (PMID 39735599, 2024). "Knocking down ILF2 expression in various cancer cell lines has demonstrated inhibitory effects on tumor growth and metastasis." (PMID 39735599, 2024). "High ILF2 expression correlates with poor prognosis, advanced tumor stage, and lower OS in patients, suggesting its potential as a prognostic biomarker." (PMID 39735599, 2024). "The mice were randomized based on the level of tumor burden detected by bioluminescence imaging and injected daily with NT or ILF2 ASOs for 7 days." (PMID 38331987, 2024). "For example, ILF2 has been shown to enhance tumor cell proliferation by regulating the cell cycle and inhibiting apoptosis." (PMID 39735599, 2024). "Beyond serving as a biomarker, ILF2’s role in tumor progression makes it a promising therapeutic target." (PMID 39735599, 2024). "In this context, ILF2 has emerged as a potential key player in tumor biology due to its multifaceted roles in gene regulation and cellular function." (PMID 39735599, 2024). "H19 or ILF2 depletion led to a drastic reduction in tumor volume, suggesting that H19 and ILF2 promote tumor progression." (PMID 37298108, 2023). "Further investigation of the TNMplot database revealed that the expression of ILF2 was increased in oral tumor tissue and was closely related to tumor metastasis." (PMID 35333683, 2022). "By using TNMplot database, ILF2 was uncovered to possess increased expression in oral tumor tissues and was closely related to tumor metastasis." (PMID 35333683, 2022). "At the same time, higher expression of HCG18, HMGA1, ILF2, and YBX1 was associated with a higher stem cell score and less tumor differentiation." (PMID 34527669, 2021). "31B was significantly lower expressed while LSM4 and ILF2 were significantly higher expressed in tumor versus matched normal mammary gland tissue." (PMID 30940821, 2019). "circ-ILF2, circCRIM1 and circTPST2 may also play a role in modulation of the tumor microenvironment." (PMID 40176914, 2025). "ILF2 enhances tumor cell migration and invasion, contributing to tumor metastasis." (PMID 39735599, 2024). "Moreover, the addition of α-KG reversed the inhibitory effect of ILF2 knockdown on tumor size and growth." (PMID 38238853, 2024). "Consistent with our hypothesis, the mice that received ILF2 ASOs in combination with NSC had a significantly lower tumor burden than those that received NT ASOs in combination with NSC." (PMID 38331987, 2024). "ILF2 enhances tumor cell proliferation and survival through various mechanisms." (PMID 39735599, 2024). "Moreover, ILF2’s role in regulating the stability of mRNAs and miRNAs positions it as a crucial factor in gene expression regulation within tumor cells." (PMID 39735599, 2024). "This overexpression suggests that ILF2 may function as an oncogene, promoting tumor growth, survival, and metastasis." (PMID 39735599, 2024). "Developing drugs or genetic therapies that inhibit ILF2 expression or function could suppress tumor growth, induce apoptosis, and reduce metastasis." (PMID 39735599, 2024). "The significant difference in ILF2 expression between tumor tissues and adjacent normal tissues suggests that measuring ILF2 levels could aid in the detection and prognosis of cancers." (PMID 39735599, 2024).
tumor (continued). "Through bioinformatics analysis, we discovered a strong correlation between ILF2 expression levels in GC tissues and tumor immunity, encompassing immune cell infiltration, expression of immune checkpoint genes, immunotherapy response, as well as chemosensitivity." (PMID 38622522, 2024). "ILF2 also plays a role in key signaling pathways crucial for tumor survival and metastasis." (PMID 39735599, 2024). "In addition, we found that ILF2 was upregulated in tumour tissues compared with normal tissues in the TCGA‐BRCA dataset." (PMID 38943472, 2024). "ILF2 indirectly promotes tumor angiogenesis by upregulating pro-angiogenic factors." (PMID 39735599, 2024). "In addition, increased NUSAP1 and DHX9 mRNA levels were significantly correlated with higher tumor Gleason scores, while increased ILF2 were less correlated with tumor Gleason scores." (PMID 37047232, 2023). "In addition, circPOK of zbtb7a functions as a proto‐oncogenic RNA by co‐activating the ILF2/3 complex, which operates separately and antithetically with the linear mRNA which serves as a tumor suppressor." (PMID 32608539, 2020). "Moreover, the results also revealed that expression of ILF2 was correlated with tumor size (p = 0.043)." (PMID 27556459, 2016). "Similarly, circ-ILF2 augments the drug efflux, modulates the tumor microenvironment and DNA damage." (PMID 40176914, 2025). "To evaluate whether ILF2 ASOs sensitized MM cells to DNA-damaging agents, we further treated the xenografts with NT or ILF2 ASOs every other day in combination with melphalan and evaluated tumor burden at the end of the third cycle of the combination therapy." (PMID 38331987, 2024). "Thus, targeting ILF2 could disrupt these pathways, providing a novel approach to inhibit tumor progression." (PMID 39735599, 2024). "In addition, T3 had 120 mutations not found in the other tumours, including, for example, variants in ILF2 and IL7R, which regulate immune function, and in EP400 and POU2F1, which contribute to DNA repair mechanisms." (PMID 34299215, 2021). "In addition, the role of ILF2 as a tumor promoter has also been recognized." (PMID 28831206, 2017). "In vivo, overexpression of ILF2 could promote tumor growth in a xenograft model." (PMID 27556459, 2016). "Therefore, overexpression of ILF2 might provide a beneficial effect to tumor cells during tumor progression." (PMID 27556459, 2016). "Western blotting revealed significantly elevated levels of CCNA2, CSRP2, ILF2, KIF2C, RACGAP1, and VARS proteins in HCC tissues compared to adjacent non-tumor tissues." (PMID 41323394, 2025). "Specifically, hepatocytes at the tumor periphery predominantly expressed TFs such as ILF2, ATF7, and RFXANK, while those in the tumor core were enriched for KLF4, EGR1, and HES5." (PMID 40474968, 2025). "Regarding other types of cancer, in pancreatic carcinoma miR-7 is involved in the regulation of the ILF2 oncogene in the epithelial–mesenchymal transition in PANC-1 cells, functioning as a supposed pro-tumor factor." (PMID 36012357, 2022). "HMGA1 and ILF2 were highly expressed in tumor stem cell-like cells, while YBX1 was highly expressed in both monocyte macrophages and tumor stem cell-like cells." (PMID 34527669, 2021). "HCG18 participates in vascular invasion of HCC by regulating macrophages and tumor stem cells through three key transcription factors, YBX1, ILF2, and HMGA1." (PMID 34527669, 2021). "The tumor stem cell score based on the one-class logistic regression (OCLR) algorithm showed that HCG18 and its regulated transcription factors HMGA1, ILF2, and YBX1 positively correlated with the degree of tumor undifferentiation." (PMID 34527669, 2021). "RAM+ cells were governed by ZFP42 and IRF8 maintaining anti-tumor immunity, while RAM- cells controlled by ILF2 and ISL1 promoted metastasis and immune evasion, with RAM- malignant cells enriched in patients over 65 years and associated with immunotherapy resistance." (PMID 42304383, 2026).
tumor (continued). "Despite Pokemon acting as a tumor suppressor, circPOK in the nucleus and cytosol promoted the development of tumors through the interaction with ILF2 and ILF3 and the coactivation of ILF2/3, which bound II6 promoter regions." (PMID 37953502, 2024). "Silencing ILF2 expression in PDAC inhibited cell cycle progression and decreased the expression of cell cycle regulators like cyclin E1 (CCNE) and proliferating cell nuclear antigen (PCNA), hindering tumor cell proliferation." (PMID 39735599, 2024). "While some studies have begun to elucidate the pathways involving ILF2, such as its interaction with ILF3 and regulation of miRNA processing, there remains a lack of comprehensive insight into its functions across different tumor types." (PMID 39735599, 2024). "The mice were randomized based on their bioluminescence-based tumor burden and then treated for 1 week with NT or ILF2 ASOs in the presence or absence of NSC." (PMID 38331987, 2024). "Although the regulation and function of ILF2 have been extensively investigated, the biological functions as well as the molecular mechanisms of ILF2 in tumorigenesis and tumor progression have not been fully demonstrated." (PMID 27556459, 2016). "Western blot analysis substantiated these findings at the protein level, revealing significantly elevated expression of CCNA2, CSRP2, ILF2, KIF2C, RACGAP1, and VARS in HCC tissues versus adjacent non-tumor tissues." (PMID 41323394, 2025).